CD74 (CD74 molecule)
Diseases named in the same sentence as CD74 in open-access papers (continued):
Sharing a sentence is not in itself a finding about the gene and the disease.
glioma (41 papers, 2009 to 2025). A benign or malignant brain and spinal cord tumor that arises from glial cells (astrocytes, oligodendrocytes, ependymal cells). "The MIF signaling axis on CD74/CXCR4 was found to be upregulated in glioma infiltrating macrophages and has been implicated in brain tumorigenesis by impeding microglial polarization." (PMID 38515213, 2024). "A previous study in gliomas reported that a high expression of CD74 was positively associated with secretions of inflammatory cytokines." (PMID 37629174, 2023). "Since high expression of CD74 in gliomas has been validated for the association with poor prognosis and high immune infiltrates." (PMID 35585639, 2022). "CD74 expression has been reported to be confined to microglia/macrophages in glioma and as marker associated with response to TMZ therapy, highlighting the interdependency between immune system and therapy efficacy." (PMID 35158950, 2022). "The expression of CD74 was significantly positively associated with stromal and immune scores of gliomas (p < 0.05)." (PMID 34540893, 2021). "Previous studies revealed that CD74 was associated with glioma malignancy and activity of glioma-associated macrophages." (PMID 34540893, 2021). "It was found that expression levels of CD74 in high grade gliomas were inversely associated with TMZ resistance in GBM xenograft lines, suggesting a role in TMZ resistance." (PMID 29168083, 2018). "CD74 overexpression has been observed in several non-central nervous system cancers, where it was associated with aggressive behavior and poor prognosis, whereas in GBM its potential role in temozolomide resistance has been reported." (PMID 25356585, 2014). "The upregulation of CD74, which acts as a key signal in the immune process, is associated with poor prognoses, as has been demonstrated in gastric cancer, pancreatic cancer, and glioma." (PMID 37905960, 2023). "Previous studies indicated that CD74 was highly expressed in high-grade gliomas, and it was associated with the microenvironment of glioma and could facilitate the proliferation of glioma cells." (PMID 34540893, 2021). "However, additional experiments would help provide a better understanding of the underlying mechanism of CD74 in the development and progression of gliomas." (PMID 34540893, 2021). "Since IDH mutation, MGMT methylation, and 1p19q codeletion indicated high malignancies and poor prognosis, the expression of CD74 might be associated with glioma malignancies." (PMID 34540893, 2021). "Moreover, CD74 represents a positive prognostic marker most probably because of its association with an M1-polarized immune milieu in high-grade gliomas." (PMID 34671548, 2021). "Besides, CD74 was positively associated with immune infiltration in the glioma immune microenvironment." (PMID 34540893, 2021). "Therefore, the infiltration of macrophages, dendritic cells, and neutrophils indicated high malignancy of glioma, which was consistent with our findings that CD74 was positively associated with the malignancy of glioma and the infiltration of macrophages, dendritic cells, and neutrophils." (PMID 34540893, 2021). "Silencing of CD74 by shRNA was associated with reduced AKT and ERK1/2 pathways and in the human glioma U87 cell line, significantly suppressed proliferation and increased temozolomide sensitivity." (PMID 38178143, 2024). "Analysis of CNVs on TIDE showed longer survival in patients with higher CD74 CNVs in glioma, LIHC, and DLBC but reduced survival in TNBC, LUAD, and SKCM." (PMID 38582956, 2024). "Studies have demonstrated that inhibition of the MIF/CD74 axis in gliomas will promote M1 phenotype polarization of microglia and exert anti-tumor effects." (PMID 38685050, 2024). "Macrophages critically influence glioma formation, maintenance, and progression, and CD74 is the master regulator of macrophage functions in glioblastoma." (PMID 37129360, 2023).
glioma (continued). "A recent study showed that brain tumors utilize CD74 activation to escape pro-inflammatory M1 conversion, indicating that CD74 is closely related to the glioma immune microenvironment." (PMID 36599974, 2023). "To examine the function of CD74 in macrophages in gliomas, we used CD74 as the target gene and selected 50 genes from genes expressed in >50% of macrophages isolated from glioblastoma patients." (PMID 37129360, 2023). "MIF interacted with CD74 to promote M2 immunosuppressive shift and inhibit M1 polarization, resulting in glioma development." (PMID 36387901, 2022). "In grade II and III gliomas, CD74 had a distinct expression pattern in TCGA, CGGA, and CGGA301 datasets but not in GSE108474 dataset." (PMID 34540893, 2021). "Our study revealed that CD74 was highly expressed in the high-grade glioma and correlated with poor prognosis of glioma patients." (PMID 34540893, 2021). "Through the analysis based on a large number of samples, our study would provide a novel insight into the immune characteristics of CD74 in gliomas and reveal a potential therapeutic target as well as a biomarker for gliomas." (PMID 34540893, 2021). "The IHC showed that the expression of CD74 was higher in the higher grade of glioma and was highest in grade IV glioma specimens." (PMID 34540893, 2021). "The results of the DEG co-expression network showed that the HLA family (HLA-A, HLA-B, HLA-C, HLA-E, HLA-DRA, HLA-DRB1, and CD74 [HLADG]) plays a vital role in the network, suggesting that tumor immunity is involved in glioma formation." (PMID 34660294, 2021). "Apart from the immune features, CD74 also exhibited prognostic and predictive values in the OS of glioma patients." (PMID 34540893, 2021). "Kaplan-Meier analysis revealed that the high expression of CD74 indicated poor prognosis in patients with gliomas and LGG (p < 0.05)." (PMID 34540893, 2021). "The high expression of CD74 was significantly higher in glioma tissue compared to the normal tissue." (PMID 34540893, 2021). "At a single-cell level, male microglia were found to express MHCII and CD74 genes at a higher level than female microglia in experimental murine gliomas and human gliomas." (PMID 33809675, 2021). "Apart from the RNA level, we also investigated the expression of CD74 at the protein level in different grades of gliomas." (PMID 34540893, 2021). "Our study collected 40 glioma specimens and extracted 2,399 glioma samples from the online databases to explore the expression pattern of CD74 in gliomas." (PMID 34540893, 2021). "We extracted data from The Cancer Genome Atlas (TCGA), Chinese Glioma Genome Atlas (CGGA), and Gene-Expression Omnibus (GEO) databases to explore the expression pattern of CD74 in gliomas." (PMID 34540893, 2021). "Receiver operating characteristic analysis was used to evaluate the predictive accuracy of CD74 in glioma diagnosis and prognosis." (PMID 34540893, 2021). "Since high expression of CD74 indicated low tumor purity, we further explored the clinical significance of CD74 in glioma patients." (PMID 34540893, 2021). "Then, we screened the co-expressed genes of CD74 to further characterize the immune feature of CD74 in gliomas." (PMID 34540893, 2021). "To sum up, we conducted a large-scale analysis to characterize the immune and clinical features of CD74 in gliomas." (PMID 34540893, 2021). "To characterize the role of CD74 in gliomas, we explored the expression pattern of CD74 in gliomas and normal tissue." (PMID 34540893, 2021). "CD74 expression indicated low tumor purity and high infiltration of immune cells in the glioma microenvironment." (PMID 34540893, 2021). "Our study aims to comprehensively explore the role of CD74 in glioma prognosis and immune microenvironment." (PMID 34540893, 2021).
glioma (continued). "In order to identify a potential targeted therapy that acts on the MIF/CD74 signaling axis and neutralizes M-MDSCs, we utilized the in vitro co-culture system to generate glioma educated MDSCS in the presence of different small molecule MIF inhibitors." (PMID 32625208, 2020). "Moreover, CD74 was shown to play a crucial role in dendritic cells and macrophages in the context of metastatic melanoma and glioma, reprogramming these cells to become tolerogenic and shift towards an M2 polarization." (PMID 39576827, 2024). "Besides, the MIF/CD74 signaling inhibits the IFN-γ secretion by promoting ERK1/2 phosphorylation in glioma." (PMID 38685050, 2024). "A recent experimental study by Alban and colleagues has found that the monocytic subset of myeloid-derived suppressor cells (M-MDSCs) expresses high levels of CD74 in the presence of glioma-derived macrophage migration inhibitory factor (MIF) and glioma cells (Molecular event 5)." (PMID 36555253, 2022). "In particular, gliomas may escape the pro-inflammatory M1 conversion of macrophages/microglia via CD74 activation by MIF, a mechanism that contributes to shape the contexture of GBM." (PMID 34646780, 2021). "CD74 was highly expressed in glioma tissue compared to normal brain tissue and its expression was significantly higher in the high-grade glioma compared to the lower grade glioma at transcriptional and translational levels." (PMID 34540893, 2021). "Moreover, CD74 was highly expressed in the mesenchymal subtype, which was the most malignant molecular subtype of glioma." (PMID 34540893, 2021). "In glioma and LGG patients, CD74 was significantly associated with survival rates." (PMID 34540893, 2021). "Therefore, Kruskal-Wallis test revealed that the expression of CD74 was significantly elevated in grade IV glioma compared with grade II and III gliomas in the TCGA, CGGA, CGGA301, and GSE108474 datasets (p < 0.05)." (PMID 34540893, 2021). "CD74 could be used as a potential target for glioma treatment and as a biomarker to predict the prognosis of glioma patients." (PMID 34540893, 2021). "In vivo analysis of M-MDSCs in the tumor microenvironment using the syngeneic glioma model further supports these findings by showing the mean fluorescence intensity (MFI) of CD74 as higher on M-MDSCs compared to G-MDSCs or microglia of the tumor bearing hemisphere." (PMID 32625208, 2020). "Importantly, activation of microglial CD74 weakens the microglial defense against glioma cells." (PMID 36555253, 2022). "Besides, the protein level of CD74 was markedly elevated in the higher-grade glioma." (PMID 34540893, 2021). "However, CD74 still had some merits in predicting the diagnosis and prognosis of gliomas and could be used as a potential target for glioma treatment." (PMID 34540893, 2021). "Moreover, CD74 exhibited moderate accuracy in predicting the OS of glioma patients." (PMID 34540893, 2021). "Moreover, multivariate analyses indicated that CD74 was an independent risk factor for glioma patients in the TCGA, CGGA, and GSE108474 datasets, but not in the CGGA301 dataset." (PMID 34540893, 2021). "The MIF signals sent by glioma cells (Clusters C1, C2 and C4) were mainly received by TAMs (Cluster C0) via receptors CD74 and CXCR4, and by lymphocytes (Cluster C6) via CD74, CXCR4 and CD44." (PMID 38515213, 2024). "In both lower-grade glioma (LGG) and GBM, the expression of CD74 was significantly higher compared to the normal tissue (p < 0.05)." (PMID 34540893, 2021). "CD74 was also identified as a potential modulator of TMZ responsiveness, and its shRNA-mediated knockdown, in MGMT methylated glioma cells, significantly increased sensitivity to chemotherapy." (PMID 34646780, 2021). "Therefore, CD74 might serve as a biomarker to predict the malignancy of glioma." (PMID 34540893, 2021).
glioma (continued). "Recently it has been found that in both murine and human models, M-MDSCs express high levels of the CD74 MIF receptor and are localized in the glioma microenvironment, in contrast to granulocyte-MDSCs (G-MDSCs) which show minimal accumulation in the tumor environment." (PMID 38178143, 2024). "Additionally, CD74 exhibited moderate predictive accuracy in the diagnosis of GBM and the prognosis of glioma patients." (PMID 34540893, 2021). "The top 20 co-expressed neighbors were selected, and the core genes PFN1, CALR, thymosin beta 10 (TMSB10), HLA.A, CD74 (HLADG), HLA.DRA, HLA.B, TUBB, and TUBA1A were found to play pivotal roles in the network, suggesting that immune genes are involved in glioma formation." (PMID 34660294, 2021). "In addition, we tested the human glioma expression data from The Cancer Genome Atlas (TCGA) to determine if sex has an impact on the expression of MHCII and CD74 genes." (PMID 33608526, 2021). "The analysis of TCGA and scRNA-seq human glioma data sets showed sex-related differences in MHCII complex and CD74 genes in WHO grade II diffusive gliomas, where antitumor immunity may influence outcomes." (PMID 33608526, 2021). "Fibroblast growth factor 4 (FGF4) also has been correlated with a greater malignancy profile in high-grade gliomas.The radioresistant cells had upregulated expression of many anti-apoptotic genes, including BCL2, CD74, and WT1, which regulates GBM cells proliferation and apoptosis." (PMID 30344926, 2018). "The markers for this population are largely expressed only in glioma cells (e.g., NFIB, MAP1B, TUBB2B) and they express low levels or have no expression of myeloid/immune markers (CD74, APOE, HLA genes, and CD45)." (PMID 40588233, 2025). "In different subtypes of glioma, the expression of CD74 was significantly higher in the IDH wildtype and 1p19q non-codeletion gliomas (p < 0.05)." (PMID 34540893, 2021). "CD74 was highly expressed in grade IV, IDH wildtype, 1p19q non-codeletion, and MGMT unmethylated gliomas." (PMID 34540893, 2021). "Although the low CD74 expression in the LN18 cells most likely account for the unresponsiveness to exogeneous MIF, a different glioma cell line not expressing CD74 has been found to still be responsive to recombinant MIF - arguing for an alternative MIF receptor." (PMID 20038293, 2009).
lung carcinoma (38 papers, 2013 to 2025). "Although CD74 overexpression is mostly associated with hematologic malignancies, it has also been reported in non‐hematopoetic cancers such as gastric, renal, urinary bladder, non‐small cell lung cancer certain sarcomas and glioblastomas." (PMID 37081824, 2023). "In this lung cancer dataset, we found that ASPs in CD74 were exclusively dominated by the isoforms CD74-201 and CD74-202." (PMID 40990037, 2025). "The feature scores output by the model can effectively distinguish the level of CD74 expression, providing a new indicator for prognosis stratification and individualized precision treatment of lung cancer patients." (PMID 40470045, 2025). "Among ROS1-positive lung cancers, we also observed that CD74::ROS1 tumors had more fusion subclones than ROS1 tumors with other fusion partners." (PMID 40041857, 2025). "For example, lung cancers with HLA-DR or CD74 fusions are most likely to originate in cells that express these genes robustly, such as alveolar type II cells." (PMID 38877018, 2024). "CD74 fusion proteins mainly manifest in lung cancer, apart from a single documented case in an aggressive case of inflammatory breast cancer and two cases of pediatric leukemia." (PMID 37958963, 2023). "Noteworthily, the majority of CD74 fusion proteins found in patients were first reported in lung cancers, and the same trend continues to date." (PMID 37958963, 2023). "CD74 is a type II transmembrane protein with various biological functions that promote the angiogenesis of lung cancer cells when co-expressed with macrophage migration inhibitory factor (MIF)." (PMID 37745301, 2023). "YAP1 was also proven to be related to the multidrug resistance of lung cancer by CD74-related signaling pathways." (PMID 36428672, 2022). "In lung cancers, fusions with CD74 (83/216, 38.4%), EZR (28/216, 13.0%), SDC4 (26/216, 12.0%), and SLC34A2 (26/216, 12.0%) were highly frequent." (PMID 36369474, 2022). "More than 30 ROS1 fusion gene partners have been reported in lung cancer, glioma, and hepatic angiosarcoma, containing CD74, SLC34A2, GOPC." (PMID 36589752, 2022). "Although CD74 was the most common partner in lung cancer, only EZR-ROS1 and SDC4-ROS1 fusions were found in SCC." (PMID 34508169, 2021). "For example, in a large cohort study of 10,966 Chinese NSCLC patients, the frequency of NRG1 fusions was only 0.16% in these unselected lung cancer patients, with CD74 being the most common fusion partner." (PMID 33505917, 2020). "Our ROGUE-guided analysis on fibroblasts identified a novel subpopulation in lung cancer, apCAFs, which highly expressed CD74 as well as MHC class-II genes and had a strong antigen-presenting signal." (PMID 32572028, 2020). "NTRK1 (Neurotrophic Receptor Tyrosine Kinase 1; encodes TrkA) was previously reported to impose oncogenic activity in lung cancer cells by fusing with CD74 and, independently, with MPRIP." (PMID 29568375, 2018). "In lung cancer, CD74 was mainly detected in the stromal compartment or in stromal and epithelial cells." (PMID 24939415, 2014). "CD74 is overexpressed in a wide variety of cancers (gastric, thymic, colorectal, breast, renal and lung carcinomas, invasive thymomas, bladder, prostate and pancreatic cancers)." (PMID 25304249, 2014). "In particular, NTRK1 has been found to fuse with tropomyosin in colon cancer, TPM3, TPR, and TFG in thyroid cancer, and MPRIP and CD74 in lung cancer." (PMID 24647444, 2014). "Although very little is known of the relevance of CD74 in many lung cancers, the expression of CD74 in gastric carcinoma has been associated with a poor prognosis." (PMID 23522304, 2013). "Translocations involving CD74 have also been observed in lung cancer." (PMID 40670673, 2025). "Interestingly, one recent study showed that lung cancer patients with CD74::ROS1 had a lower survival rate compared to those with other ROS1 partners." (PMID 40041857, 2025).